IGKV2D-26 (immunoglobulin kappa variable 2D-26)
Description:
V region of the variable domain of immunoglobulin light chains that participates in the antigen recognition. Immunoglobulins, also known as antibodies, are membrane-bound or secreted glycoproteins produced by B lymphocytes. In the recognition phase of humoral immunity, the membrane-bound immunoglobulins serve as receptors which, upon binding of a specific antigen, trigger the clonal expansion and differentiation of B lymphocytes into immunoglobulins-secreting plasma cells. Secreted immunoglobulins mediate the effector phase of humoral immunity, which results in the elimination of bound antigens. The antigen binding site is formed by the variable domain of one heavy chain, together with that of its associated light chain. Thus, each immunoglobulin has two antigen binding sites with remarkable affinity for a particular antigen. The variable domains are assembled by a process called V-(D)-J rearrangement and can then be subjected to somatic hypermutations which, after exposure to antigen and selection, allow affinity maturation for a particular antigen.
Synonyms: A5; IGKV2D26
Gene: Immunoglobulin variable (V) gene on chromosome 2 (89,985,922 to 89,986,702, forward strand). Ensembl gene ENSG00000211623.
Subcellular location: Secreted; Cell membrane
Gene Ontology:
Biological process: immune response
Cellular component: extracellular region; immunoglobulin complex; plasma membrane
Homologues: Orthologues: mouse Igkv2-109 (68% identical). Paralogues in human: IGKV2D-29 (84% identical), IGKV2-28 (79% identical), IGKV2D-28 (79% identical), IGKV2D-40 (79% identical), IGKV2-24 (76% identical), IGKV2-30 (75% identical), IGKV2D-24 (75% identical), IGKV2D-30 (74% identical), IGKV2-40 (65% identical), IGKV3-20 (58% identical), IGKV3-11 (57% identical), IGKV3D-20 (57% identical), and 81 more.
Diseases named in the same sentence as IGKV2D-26 in open-access papers:
IGKV2D-26 is named in the same sentence as 6 diseases in open-access papers, as found by Europe PMC text mining. Sharing a sentence is not in itself a finding about the gene and the disease.
IGKV2D-26 shares sentences with these, for which no sentence is quoted: cancer (1 paper); epilepsy (1); Hyperglycemia (1); infection (1); latent infection (1); tumor (1).